CRP (C-reactive protein)
Diseases named in the same sentence as CRP in open-access papers (continued):
Sharing a sentence is not in itself a finding about the gene and the disease.
Hypertension (continued). "In Multivariable Mendelian randomization, factors such as cigarettes per day, alcoholic drinks per week, hypertension, body mass index, type 2 diabetes, C-reactive protein, rheumatoid arthritis were incorporated to further account for the independent causal effects of multiple correlated exposures." (PMID 39787159, 2025). "Considering that systemic inflammatory biomarkers such as C-reactive protein (CRP) and leukocyte count correlate with both periodontitis and hypertension, it is hypothesized that systemic inflammation may mediate the relationship between the two diseases." (PMID 40572711, 2025). "However, biomarkers of inflammation are elevated in individuals with hypertension, including high-sensitivity C-reactive protein (hs-CRP), various cytokines, and complement pathway products." (PMID 40572711, 2025). "Significant differences were observed between the two groups in terms of DII score, gender, age, ethnicity, education level, drinking status, PA level, BMI, WC, waist-to-height ratio (WHtR), SI, SVR, PIR, lymphocytes, neutrophils, CRP, and histories of DM, hypertension, and stroke (all p < 0.05)." (PMID 40860482, 2025). "CRP is a marker of systemic inflammation, often elevated in hypertension, and may contribute to vascular dysfunction, with elevated levels of both IL-6 and CRP found in patients with dilated left atria." (PMID 40005478, 2025). "As expected, the two metabolic clusters showed very distinctive patterns in a broad spectrum of metabolic phenotypes, including age, sex, BMI, body fat percentage, waist-to-hip ratio, CRP, lipid, glucose and insulin levels, blood pressure measurements and prevalence of T2D or hypertension." (PMID 39834614, 2025). "Chronic inflammation, marked by elevated CRP levels, is a key contributor to hypertension." (PMID 41459237, 2025). "The LASSO regression results identified 15 potential variables associated with IKPLAS, including: DM, Drink, Prior history of biliary disease, Hypertension, Underlying heart disease, Fever, PLT, CRP, AST, TBIL, Creatinine, Broth culture, Abscess location, Pleural effusion, and Ascites." (PMID 41393139, 2025). "Systemic inflammatory cytokines and CRP serve as biomarkers linking periodontitis and hypertension." (PMID 40002786, 2025). "Additionally, individuals with DM exhibited a higher BMI, a history of hypertension, a greater prevalence of sleep apnea, shorter sleep duration, and elevated levels of CRP." (PMID 40557002, 2025). "Relative to the non-DFU group, DFU patients had worse metabolic and vascular profiles, with higher prevalence rates of retinopathy, neuropathy, stroke, and hypertension, as well as significant abnormalities in laboratory measures such as glycohemoglobin, CRP, creatinine, and hemoglobin." (PMID 41473241, 2025). "Univariate analysis identified the following factors as being related to the occurrence of DWI lesions: history of hypertension, use of antihypertensive medication, history of malignancy, hemoglobin concentration, fasting blood glucose, C-reactive protein, and hematoma site." (PMID 40761645, 2025). "In parallel, IL‐6 and C reactive protein plasma levels were associated with BPV in hypertensive patients, suggesting systemic inflammation as a pathophysiological mechanism contributing to TOD in hypertension." (PMID 40454610, 2025). "While this approach improves model parsimony, it may exclude clinically important but statistically borderline variables, such as hypertension, CRP, and prior stroke or TIA." (PMID 41431089, 2025). "Among patients with hypertension, the serum levels of CRP (each 0.1 mg/dL increment, odds ratio [OR]: 1.649, 95% confidence interval [CI]: 1.138–2.389, p = 0.008) and PCS (OR: 1.154, 95% CI: 1.013–1.315, p = 0.031) were identified as independent predictors for PAD." (PMID 40361914, 2025).
Hypertension (continued). "The analysis revealed that DM, Drink, Prior history of biliary disease, Hypertension, Underlying heart disease, Fever, PLT, CRP, AST, TBIL, Creatinine, Broth culture, Pleural effusion, and Ascites were all correlated with the occurrence of IKPLAS in liver abscess patients." (PMID 41393139, 2025). "Systemic inflammation, assessed through two commonly measured biomarkers (hs-CRP and white blood cell count [WBC]), was independently associated with periodontitis, systolic blood pressure, and diagnosed hypertension and was found to play a mediating role in these associations." (PMID 40572711, 2025). "The DASH diet has been proven to reduce hypertension and also decrease other antigens like CRP." (PMID 41280310, 2025). "Model III, which further adjusted for Cr, RBS, CRP,TC, HDL-C, LDL-C, and HbA1c levels based on Model II, still showed a significant association between TG level and hypertension (OR = 1.23, 95% CI: 1.03–1.47), indicating that TG level is an independent risk factor for hypertension." (PMID 41584291, 2025). "Hs-CRP levels were also significantly higher among individuals with each component of MetS, including central obesity (1.18 vs. 0.73), hypertension (1.01 vs. 0.80), high blood glucose (1.01 vs. 0.82), hypertriglyceridemia (0.96 vs. 0.84), and low HDL cholesterol (1.01 vs. 0.82) (all p < 0.001)." (PMID 40474309, 2025). "However, the high CRP group demonstrated significantly elevated rates of recurrence within one year, rehospitalization, infection frequency, secondary hypertension, renal insufficiency, and cumulative steroid use compared to the low CRP group." (PMID 40078589, 2025). "The predictors were history of hypertension (p < 0.012), elevated CRP (p < 0.002), impaired LV-GLS (p < 0.001), LV diastolic dysfunction (p < 0.001), impaired RV-GLS (p < 0.01), reduced TAPSE (p < 0.001), abnormal rMSSD (p < 0.01) and abnormal SDNN (p < 0.0001)." (PMID 39148011, 2024). "The independent risk factors for ACM were determined using multivariate Cox analysis in the main model comprising traditional risk factors (sex, dialysis vintage, history of cardiovascular diseases, and hypertension) and univariate risk factors (age, DM, GNRI, ERI, CRP level, and TG level)." (PMID 38769120, 2024). "Hypertension and the use of medications such as angiotensin II receptor blockers or calcium channel blockers were associated with higher CRP levels after closure, but they did not explain the differences between the groups either (p<0.001 for all)." (PMID 38184301, 2024). "The adjusted for age, BMI, current smoking, and a number of chronic diseases (excluding hypertension) OR for high BP was 1.32 (95% CI, 1.05 to 1.66, P = 0.02) and 1.41 (95% CI, 1.13 to 1.76, P = 0.002) for highest vs. lowest quartiles of hs-CRP and WBC, respectively." (PMID 38720047, 2024). "In addition, the presence of high CRP levels is associated with a higher risk of developing hypertension in the general population, whereas individuals with high CRP levels have greater hypertension-related complications than those with low CRP levels." (PMID 38792613, 2024). "A natural substance that reduced CRP and proinflammatory, IL6 and TNFα were used as complementary therapy for managing rheumatoid arthritis, a chronic inflammatory condition associated with an increased risk of hypertension." (PMID 39558500, 2024). "In order to limit the possible influence of baseline covariate imbalances on our outcome, we additionally conducted propensity-score-weighted logistic regression analysis for sex, hypertension, age (z-score), BMI (z-score), creatinine (z-score), CRP (z-score), pBNP (z-score), and EF (z-score)." (PMID 39064192, 2024). "Additionally, it has also been demonstrated that hs‐CRP level was generally higher in those who were obese, dyslipidemic, and suffer from hypertension." (PMID 38628050, 2024).
Hypertension (continued). "Remarkably, these patients with AKI exhibited an advanced age (>65 years), arterial hypertension, a higher number of white blood cells during admission and the hospital stay, and elevated levels of C-reactive protein, serum creatinine, and blood urea nitrogen (BUN)." (PMID 38804444, 2024). "Second, we assessed major traditional risk factors such as hypertension and DM but did not include novel risk factors such as C-reactive protein or lipid profiles." (PMID 39064011, 2024). "Adjusted Cox models for age, male, BMI, hypertension, hyperlipidemia, smoking, hs-CRP, eGFR." (PMID 39060937, 2024). "Moreover, we confirmed that patients who underwent mechanical ventilation had a longer illness time, higher hypertension, less CRP and albumin, higher amounts of urea, and worsened pulmonary function (according to the PaO2/FiO2 and A-a O2 gradients)." (PMID 38838044, 2024). "Sex, age, marital status, educational level, PIR, smoking, hypertension, severe headache or migraine, energy, protein, carbohydrate, vitamin A, vitamin C, vitamin E, carotenoid, zinc, selenium and CRP in the different quartiles were found to have statistically significant differences (p < 0.05)." (PMID 39148702, 2024). "Patients with MACE exhibited significant differences in ALC, ALB, preoperative PNI, age, BMI, CRP, TG, presence of comorbidities (hypertension, hyperlipidemia, pulmonary infections), history of prior PCI, smoking status, LVEF, Cr, and intervention programs, in comparison to those without MACE." (PMID 39068452, 2024). "Several studies have shown a positive correlation between CRP and hypertension." (PMID 38791032, 2024). "The patients included in cluster 2 were older, had more hypertension, shock, inflammation measured by CRP, and better respiratory indexes (including the requirement of the prone position, NMBA requirement, oxygenation by Pao2/Fio2, ventilatory ratio, and driving pressure)." (PMID 38515193, 2024). "Of the 32,464 participants aged ≥ 20 years, 30,232 were excluded because they had no history of cancer (n = 29,470), were less than 40 years of age (n = 217), had missing data for CRP (n = 407), albumin (n = 18), smoking status (n = 2), alcohol use (n = 119), and hypertension (n = 1)." (PMID 39358685, 2024). "However, in our study, the serum log-CRP levels were positively correlated with the OC levels in patients with hypertension." (PMID 38793018, 2024). "Univariate logistic regression analysis revealed that the presence of tophi was significantly associated with age, disease duration, hypertension, alcohol consumption, family history of gout, SUA, Scr, CysC, ALT, CRP, and ESR levels in male patients with primary gout." (PMID 39635582, 2024). "Moreover, compared with the nr-axSpA and control groups, r-axSpA patients had higher levels of serum CRP (p = 0.003) and a greater frequency of arterial hypertension (p = 0.001)." (PMID 38449853, 2024). "Elevations in pro-inflammatory cytokines, such as interleukin (IL)-6, IL-1β, IL-1α, IL-18, IL-2, IL-8, tumor necrosis factor (TNF)-α, interferon (IFN)-γ, C-reactive protein (CRP), and monocyte chemoattractant protein (MCP)-1, have been associated with arterial hypertension." (PMID 39519450, 2024). "Serum logarithmically transformed (log)-CRP (log-CRP) showed a positive correlation (r = 0.211, p = 0.021), whereas the eGFR exhibited a negative correlation (r = −0.208, p = 0.023) with the OC levels in patients with hypertension." (PMID 38793018, 2024). "Moreover, significantdifferences in hypertension, hyperlipidaemia, atrial fibrillation (AF) or atrialflutter, eGFR, serum Na+, D-dimer, and Hs-CRP levels, as well as intracardiacthrombosis, were observed between male patients with and without DCM-IS." (PMID 39076319, 2024). "In addition, higher DunedinPACE was associated with a higher risk of hypertension (OR > 1), as well as elevated levels of AST, ALT, TG, and hs-CRP (Beta > 0)." (PMID 39687863, 2024).
Hypertension (continued). "Consistent with our findings, the incidence of T2DM significantly increases among individuals with a family history of both hypertension and hypercholesterolemia, as well as with increased levels of inflammatory biomarkers, i.e., C-reactive protein and interleukin-6, as reported by others." (PMID 38668310, 2024). "This underscores the benefits of physical fitness on CRP levels in sedentary men with hypertension." (PMID 39246645, 2024). "Likewise, after adjusting for the status of smoking and drinking habits, BMI, history of hypertension, LDL-C, HDL-C, AST, and serum creatinine, 1.95-fold, 1.57-fold increased risk of DKA or HHS were exhibited with 1-unit increment of CRP and PCT, respectively." (PMID 38455656, 2024). "Males in the D/AO group tended to be older, more likely to live in urban areas, have lower education levels, have higher levels of CRP, and have higher prevalences of hypertension, DM, depression, and cardiovascular diseases, compared to those in the ND/NAO group." (PMID 39367987, 2024). "The final model includes covariates HIV, hyporexia, hemoglobin, CRP, and hypertension." (PMID 39536219, 2024). "Plasma CRP levels reflect systemic inflammation and could represent an important marker for the development and progress of hypertension." (PMID 37298077, 2023). "Therefore, we finally selected neutrophil count, lymphocyte count, hypertension, anterior wall myocardial infarction, proximal occlusive lesions, and CRP > 3.85 mg/L to construct a nomogram model, and the AUC of the model was 0.779 (95% CI 0.717–0.832)." (PMID 36977721, 2023). "An independent association between C-reactive protein levels and QTc prolongation has been shown, even in apparently healthy subjects or in noninflammatory heart diseases like hypertension, coronary artery disease, or Takotsubo cardiomyopathy." (PMID 37089886, 2023). "Although it is well established that CRP levels are associated with hypertension, a negative correlation between antihypertensive therapy and CRP levels was found, in contrast to other studies." (PMID 38098917, 2023). "The multivariate logistic regression model considered 14 parameters with a p < 0.05 in the univariate analysis, including age, BMI, NC, hypertension, type 2 diabetes, coronary heart disease, AE in the previous year, fibrinogen, thrombin time, CRP, mMRC, CAT, SACS, and GOLD stage." (PMID 37008211, 2023). "No statistically or clinically significant association was found between hypertension with dental status.The dental inflammation score was found to have no statistical association with the C-reactive protein." (PMID 37629193, 2023). "Previous studies like the Women’s Health Study and the Framingham Offspring Study strengthen this concept by showing that CRP could independently predict the development of new-onset hypertension." (PMID 37633936, 2023). "After further adjustment for socioeconomic status, smoking, hypertension, BMI, total cholesterol, HbA1c, CRP, and serum uric acid, the odds of nephropathy [adjusted odds ratio 2.12, 95% Cl, 1.46–3.08], PAD [4.44, 1.87–10.51] and CAD [2.35, 1.64–3.37] were higher in non-migrants than in migrants." (PMID 37664733, 2023). "Increased CRP levels precede and predict the development of hypertension and type 2 diabetes, suggesting that CRP itself may be pathophysiologically important." (PMID 37504556, 2023). "Additionally, participants with dyslipidemia were older (50.13 ± 0.28 years vs. 40.21 ± 0.36 years), with a higher CRP (0.44 ± 0.02 mg/L vs. 0.31 ± 0.01 mg/L) and likelihood for comorbidities (hypertension, DM, CAD, CHF, stroke, and cancer)." (PMID 37689717, 2023). "Our previous studies reported relationships between CP and various factors, such as vitamin intake and health-related QOL (HRQoL), hypertension and HRQoL, alcohol intake and depression, fatty acid intake and C-reactive protein levels, and hypertension and being underweight." (PMID 36829315, 2023).
Hypertension (continued). "This was consistent with the finding that CRP levels were correlated with hypertension." (PMID 37660067, 2023). "WC, HOMA-IR (surrogates of IDF diagnostic criteria for metabolic syndrome) and CRP (a marker of inflammation) were associated with CERT1, with the contribution of other parameters such as DBP/SBP, HDL-C and TG (i.e., arterial hypertension and dyslipidemia) being negligible." (PMID 37569827, 2023). "In this study, we established a predictive model and incorporated the following 12 variables into its construction: age, preoperative serum albumin, ASTI, preoperative CRP level, hypertension, IBL, IMBP, CCD, history of smoking, history of alcohol consumption, PD, and the AIMBPD." (PMID 36258311, 2023). "Moreover, our study identified several risk factors significantly associated with END, including age, sex, SBP, DBP, DM, hypertension, smoking, NIHSS, HDL, CRP, and HCY." (PMID 37248537, 2023). "It was found that hypertension, anterior wall myocardial infarction, culprit vessel, proximal occlusion, CRP > 3.85 mg/L, white blood cell count, neutrophil count, lymphocyte count, neutrophil/lymphocyte ratio > 2.17, etc., were associated with ischemia–reperfusion injury." (PMID 36977721, 2023). "In the present study, most of those who had stage 1 hypertension were in the high‐risk CRP category (CRP > 3 mg/L), and conversely, none of those with high‐risk CRP were with normal BP." (PMID 37008812, 2023). "However, dietary approaches to arrest hypertension and a plant-based dietary model have been shown to be beneficial in reducing IL-6 and CRP levels." (PMID 38077946, 2023). "In our cohort, a large proportion of this cohort had a long duration of hypertension and currently had relatively low blood pressure, which might contribute to the stable CRP secretion." (PMID 37759159, 2023). "In addition, multivariate Cox regression analysis showed that hypertension, hs-CRP, exo-circ-0020887, and exo-circ-0009590 expression were independent risk prognosticators." (PMID 37840751, 2023). "On risk factor analysis, age, hypertension, shortness of breath, IHD, CKD, high WBC, CRP, and PCT levels at admission were found to be more common in the diabetic patients than in non-diabetic patients; however, on adjusted analysis, only the age was found to be a significant risk factor." (PMID 36634951, 2023). "Also, a recent article has disclosed higher levels of IL-6, TNF-α, and hs-CRP in uncomplicated hypertension." (PMID 37759223, 2023). "Interestingly, multivariate Cox regression model showed that hypertension, hs-CRP, exo-circ-0020887, and exo-circ-0009590 expression were independent risk prognosticators." (PMID 37840751, 2023). "Additionally, another study found that after adjusting for factors related to hypertension, DM, NIHSS score at admission, and various blood laboratory indicators, END was associated with CRP and HCY levels." (PMID 37248537, 2023). "The fact that reduction in inflammation, evaluated by CRP levels, has been associated with a reduction in HMOD with uric-acid-lowering therapy in patients with essential hypertension supports this hypothesis." (PMID 37504556, 2023). "Although elevated CRP values have been previously associated with resistant and non-dipping essential hypertension, in our study the values of CRP and ESR were similar in patients with dipping and non-dipping circadian profile." (PMID 36983796, 2023). "This study aimed to examine whether the combination of elevated-C-reactive protein (CRP) levels and hypertension increased the risk of stroke among middle-aged and elderly Chinese." (PMID 36262245, 2022). "Inflammation is related to hypertension, and CRP is one of the inflammatory markers." (PMID 36418968, 2022). "In cross‐sectional analyses, some—but not all—studies have reported modest associations between CRP and various surrogate markers of early disease risk such as hypertension, metabolic syndrome, and vascular dysfunction." (PMID 35156387, 2022).